MIR6750 (microRNA 6750)
Synonyms: hsa-mir-6750
Gene: MicroRNA gene on chromosome 11 (64,898,363 to 64,898,437, reverse strand). Ensembl gene ENSG00000274986.
Homologues: Orthologues: chimpanzee MIR6750 (100% identical).